U6 (U6 spliceosomal RNA )
Gene: Small nuclear RNA gene on chromosome X (86,481,028 to 86,481,130, forward strand). Ensembl gene ENSG00000277717.
Homologues: Orthologues: chimpanzee U6 (100% identical), guinea pig U6 (64% identical), pig U6 (63% identical), pig U6 (59% identical), rat LOC120099053 (50% identical). Paralogues in human: RNU6-1047P (75% identical), RNU6-1283P (75% identical), RNU6-1060P (74% identical), RNU6-1075P (74% identical), RNU6-338P (74% identical), RNU6-434P (74% identical), RNU6-49P (74% identical), RNU6-767P (74% identical), RNU6-1007P (73% identical), RNU6-1031P (73% identical), RNU6-1040P (73% identical), RNU6-1124P (73% identical), and 1286 more.